STAT1 (signal transducer and activator of transcription 1)
Diseases named in the same sentence as STAT1 in open-access papers (continued):
Sharing a sentence is not in itself a finding about the gene and the disease.
breast cancer (continued). "The findings that diminished STAT1 expression is associated with breast cancer progression prompted us to investigate whether loss of STAT1 was a cause, not merely a consequence, of mammary tumorigenesis." (PMID 22264274, 2012). "Taken together, these data suggest that pregnancy-associated hormones might accelerate mammary tumor formation in STAT1-/- mice." (PMID 22264274, 2012). "Overexpression of the IFN/STAT1 pathway is also associated with poor prognosis in different types of cancer and may have predictive value in breast cancer patients selected for the adjuvant chemotherapy." (PMID 19503789, 2009). "Similarly, the up-regulation of STAT1 represents a serious risk for human health since its activation is able to down-regulate programmed cell death genes in several cancer cell lines (i.e., breast cancer and adenocarcinoma cells)." (PMID 34830379, 2021). "Indeed, in an ex vivo co-culture model it was demonstrated that stromal fibroblasts can secrete IFNs, activating the IFN/STAT1 pathway in breast cancer cells, and that this pathway is associated with poor prognosis in patients with breast cancer due to the development of metastases." (PMID 19503789, 2009). "Previous studies have reported that PLSCR1 can activate the STAT1 signaling pathway in breast cancer cells, suggesting a potential regulatory relationship." (PMID 41146421, 2025). "The study demonstrated that overexpression of HER2 led to increases in STAT1 and ACTA2 in EGFR+ breast cancer cells, whereas the use of the STAT1 inhibitor fludarabine resulted in decreased ACTA2 mRNA and HER2 protein levels." (PMID 40732340, 2025). "To date, only four GEMMs have been reported to develop HR+ mammary tumors: the Stat1-knockout, BLG-Cre; Kras(G12V), NRL-PRL, and Wap-Cre; Pik3ca(H1047R) models." (PMID 38913216, 2024). "In this way, STING was inactivated and subsequently decreased the secretion of inflammatory cytokines, downregulating the STAT1 and NF-κB pathways in brain metastatic cells, thereby suppressing the brain metastasis of breast cancer and lung cancer." (PMID 38654350, 2024). "Conversely, other studies determined that STAT1 promotes tumorigenesis, fostering chemoresistance and radioresistance in cancers like renal cell carcinoma, breast cancer, and myeloma." (PMID 38675812, 2024). "By modulating the expression of p-JAK2, p-STAT1 and PD-L1 in the JAK/STAT1 signaling pathway, Qu enhances the regulation of γδ T cells and improves the cytotoxic activity of immune cells against breast cancer." (PMID 39712006, 2024). "Studies revealed that PDGFR can through activated STAT1 and other distinct pathways promote mammary cancer metastasis." (PMID 38512482, 2024). "Exosome transfer from stromal cells to breast cancer cells has been identified, with RNA within these exosomes modulated radioresistance within the breast cancer cells by regulating the STAT1/NOTCH3 pathway." (PMID 39540151, 2024). "In breast cancer cell lines, it was observed that combined inactivation of STAT1 and STAT3 signaling pathways results in significant downregulation of PD-L1 expression compared to individual inhibition." (PMID 39690423, 2024). "Treatment and disease stage influenced these gene expressions, with certain subtypes, such as HSPAhi/STAT1+ macrophages in breast cancer, displaying reduced pro‐angiogenic gene activity post‐treatment." (PMID 39526457, 2024). "Briefly, SRC-1 promotes the transcriptional activityof several transcription factors, including HOXC11, PEA3, AP-1, HIF1α, c-FOS, Ets1/2, and STAT1/3, in breast cancer." (PMID 38553750, 2024). "Combined and reduced wordiness: Apigenin and its metabolite luteolin inhibit IFN-γ-induced PD-L1 expression in human and mouse breast cancer cells by suppressing STAT1 activation." (PMID 38594256, 2024). "The immunomodulatory action of quercetin is mediated through the regulation of the JAK/STAT1 signaling pathway, which facilitates the cooperative destruction of breast cancer cells." (PMID 39690423, 2024).
breast cancer (continued). "Our research demonstrated that STAT1 expression increased in breast cancer cells infected with oHSV-1, consistent with Mahller’s study." (PMID 39850819, 2024). "By modulating the production of IFN-γ-R, p-JAK2, p-STAT1, and PD-L1 in this pathway while promoting γδ T cell regulation, quercetin acts synergistically to induce apoptosis in breast cancer cells." (PMID 39690423, 2024). "MLKL expression is transcriptionally up-regulated by interferon-γ-regulatory factor 1 (IRF1) and the signal transducer and activator of transcription 1 (STAT1) in MDA-MB-231 breast cancer and HeLa cervical cancer cell lines." (PMID 38474369, 2024). "Previous studies have reported the tumor-promoting activities of STAT1 in breast cancer and leukemia among others." (PMID 39294742, 2024). "Our data show that at a concentration of ∼0.5 μg/ml IFNGR1 mAb, the protein expression levels of both total STAT1 and phosphorylated STAT1 (p-STAT1) decreased to levels comparable to those observed in unstimulated MDA-MB-231 breast cancer cells." (PMID 39262976, 2024). "In that study, IFN-γ-induced p-STAT1 in peripheral monocytes was lower in breast cancer patients who relapsed compared to those who remained relapse-free, as well as compared to healthy donors." (PMID 37741983, 2023). "Another study investigated IFN-γ signaling response via p-STAT1 in peripheral monocytes from breast cancer patients who later relapsed or remained relapse-free, and compared them to healthy donors." (PMID 37741983, 2023). "Discussion: This study identified the hsa_circ_0086735-miR-1296-5p-STAT1 as an important regulatory axis in luminal-subtype breast cancer, aiding to determine potential therapeutic targets." (PMID 37187897, 2023). "Hsa_circ_0086735 and STAT1 mRNA was upregulated in luminal breast cancer, while miR-1296-5p was downregulated." (PMID 37187897, 2023). "Together, the findings in this part of the study indicate that both STAT3 and STAT1 play key roles in mediating the cell-autonomous and PD-1-induced pro-metastatic functions of PD-L1 in breast cancer cells." (PMID 37830552, 2023). "We also revealed that, as part of the upstream regulatory mechanism, the INF-γ–STAT1 signaling axis promoted TINCR transcription in breast cancer." (PMID 36725842, 2023). "We used qRT-PCR to examine the effect of STAT1 knockdown on TINCR expression in breast cancer cells." (PMID 36725842, 2023). "ISGs, including STAT1, were found to be downregulated in blood lymphocytes from breast cancer patients compared to healthy controls via RT-qPCR." (PMID 37741983, 2023). "STAT1 was verified to accelerate breast cancer via deregulating homeostasis of the tumor microenvironment." (PMID 37187897, 2023). "Of note, both TGFB1 and STAT6 are well-known for their immune evasive roles in breast tumor microenvironment while STAT1 is proposed as a potential biomarker in breast cancer patients undergoing immune checkpoint therapy." (PMID 36809986, 2023). "This research direction was further enforced by studies demonstrating that STAT3 and STAT1 have cardinal roles in regulating cancer progression, including in breast cancer." (PMID 37830552, 2023). "For example, in breast cancer cells, STAT1 signaling activated by IFN-γ and poly(I:C) can induce an increase in oxidative stress, potentiating the anti-tumor efficacy of the mitochondrial complex I inhibitor phenformin." (PMID 38022653, 2023). "qRT-PCR was used to validate the expression levels of hsa_circ_0086735, miR-1296-5p, and STAT1 in luminal-subtype breast cancer." (PMID 37187897, 2023). "An IHC human breast cancer study demonstrated that p-STAT1 is a potential marker for selecting patients for anti-PD-1/PD-L1 immunotherapy." (PMID 37342338, 2023). "Specifically, DDR2, a force signal receptor, was found to regulate the cell cycle arrest of breast cancer cells through the upregulation of STAT1/p27 signaling." (PMID 37369642, 2023).
breast cancer (continued). "Hsa_circ_0086735-miR-1296-5p-STAT1 axis promotes breast cancer progression and contributes to tamoxifen resistance." (PMID 37187897, 2023). "Parallel experiments that were performed with MDA cells provided additional evidence for the key roles played by STAT3 and STAT1 in mediating PD-L1 functions in breast cancer cells." (PMID 37830552, 2023). "IKKβ and/or STAT1 signaling was necessary for EPS to modulate phenotypes of EPS sensitive breast cancer cells." (PMID 38074643, 2023). "Given the Spearman correlation coefficients were 0.53 and 0.58, GCH1 and STAT1 were well-correlated in breast cancer and ovarian cancer." (PMID 36793373, 2023). "In this study, we have identified key roles for members of the STAT family, namely STAT3 and STAT1, in mediating PD-L1-induced cell-autonomous and pro-metastatic activities in breast cancer cells." (PMID 37830552, 2023). "ARHGDIB and STAT1 are increased in models of breast cancer CTCs while STAB1 and TLR2 are increased in tumor-associated inflammatory cells in breast and colorectal cancer." (PMID 36176417, 2022). "An anti-tumor role of STAT1 was confirmed by studying the highly metastatic murine breast cancer cell line 4T1.2 in STAT1 null BALB/c mice." (PMID 35681772, 2022). "Strikingly, inhibition of DNMT3B reduces TIMP3 methylation levels and enhances TIMP3 protein levels, thus modulating the STAT1/FOXO1 pathway in breast cancer." (PMID 36061358, 2022). "Quercetin regulated the immunomodulatory function through the JAK/STAT1 signaling pathway, which was followed by the synergistic killing of breast cancer cells." (PMID 35379271, 2022). "Unsurprisingly, there is prior evidence to suggest that DNMT3B affects the progression of breast cancer by targeting the STAT1/FOXO1 pathway." (PMID 36061358, 2022). "Immunohistochemical (IHC) analysis of ER− versus ER+ breast tumors from patients showed that 37/83 or 45% of ER+ breast cancers had low or undetectable STAT1, while 17/78 or 22% of ER− breast cancers had low to undetectable STAT1." (PMID 35681772, 2022). "Using these STAT1-null cells, we found that STAT1 is required for IFNγ to sensitize breast cancer cells to the antitumorigenic effects of phenformin." (PMID 34083537, 2021). "IFNγ treatment modestly reduced the basal and maximal respiration rates of breast cancer cells and in a STAT1-dependent manner." (PMID 34083537, 2021). "IL-27 is the unique strong EMP inhibitor of the family by a dominant STAT1 activation, while, interestingly, its subunit p28 (IL-30) has been suggested to favour an invasive phenotype in breast cancer cells." (PMID 34361105, 2021). "Similar to the mechanism in breast cancer, both apigenin and curcumin impaired the phosphorylation of STAT1." (PMID 34819055, 2021). "In several forms of human cancer, such as breast cancers, pleural mesothelioma, head and neck cancer, and lymphoma, aberrant activation STAT1 has been identified." (PMID 33986802, 2021). "Apigenin has been shown to restrict IFN-γ-induced PD-L1 expression on both human and mouse breast cancer cells by inhibiting STAT1 phosphorylation." (PMID 34819055, 2021). "TRβ-driven tumor suppressive transcriptomic signatures include repression of known drivers of proliferation such as PI3K/Akt pathway, activation of novel signaling such as JAK1/STAT1, and metabolic reprogramming in both thyroid and breast cancers." (PMID 34503062, 2021). "In vivo studies on breast cancer revealed anti-metastatic effects of STAT1 by showing that STAT1−/−-mice displayed more lung metastases than wild-type mice." (PMID 34638338, 2021). "Combined, these observations suggest that polyIC treatment cooperates with phenformin by inducing STAT1-dependent breast cancer cell apoptosis." (PMID 34083537, 2021). "We next compared steady-state NQO1, STAT1, and pY701-STAT1 protein levels across a panel of human breast cancer cell lines spanning various subtypes." (PMID 34083537, 2021).
breast cancer (continued). "Collectively, these results demonstrate that STAT1-dependent signaling inhibits NQO1 expression in some breast cancer cells, sensitizing them to phenformin-induced oxidative stress." (PMID 34083537, 2021). "IFNγ-induced STAT1 activation cooperates with phenformin to reduce the viability of MT breast cancer cells." (PMID 34083537, 2021). "Work by Li and colleagues reflects the favorable properties of miR-29c in breast cancer by regulating the TIMP/STAT1/FOXO1 pathway." (PMID 34035375, 2021). "An ErbB2-driven breast cancer mouse model (MMTV/Neu) also responded to lapatinib treatment with increased IFNγ driven anti-tumor adaptive immune responses in a STAT1 dependent manner." (PMID 33807608, 2021). "Consistently, IFNγ-driven STAT1 activation led to a 30% reduction in the bioenergetic capacity of breast cancer cells compared to the 25-fold reduction observed with phenformin treatment, either alone or combined with IFNγ." (PMID 34083537, 2021). "STAT1 is a tumor suppressor gene in breast cancer and upregulated STAT1 expression with better response to chemotherapy in patients with ovarian cancer." (PMID 33907495, 2021). "In this study, we revealed the immunomodulatory function of Que through regulation of the JAK/STAT1 signaling pathway, which was followed by the synergistic killing of breast cancer cells." (PMID 34838003, 2021). "In high‐risk breast cancer patients, relapse‐free survival was reduced when the expression levels of ACTA2, STAT1, and HER2 were increased." (PMID 34179721, 2021). "For example, Bhlhe40 facilitates PI3K/Akt/mTOR activation and triggers tumor progression in breast cancer, whereas it represses STAT1 expression and activates tumor suppression in clear cell carcinoma." (PMID 33987177, 2021). "Increased STAT1 function potentiates oxidative stress in breast cancers, profoundly sensitizing them to the antitumorigenic effects of phenformin." (PMID 34083537, 2021). "Retinoic acid-inducible gene I (RIG-I) agonist therapy activates proinflammatory transcription factors STAT1 and NF-κB and triggers external apoptotic pathways and pyroptosis, a highly immunogenic form of cell death in breast cancer cells." (PMID 34764819, 2021). "This is partially mediated by tyrosine 239/240 and tyrosine 313 residues of Shc1, which activate STAT3-dependent immunosuppression and inhibit STAT1-induced immune surveillance in breast cancer cells, respectively." (PMID 33807608, 2021). "Here, the authors show, in breast cancer models, that inflammatory mediators can potentiate complex I inhibitor phenformin cytotoxicity through STAT1-mediated downregulation of the reactive oxygen species scavenger NQO1." (PMID 34083537, 2021). "This suggests that the ability of polyIC to sensitize breast cancers to the tumoricidal effects of phenformin requires an intact STAT1 pathway." (PMID 34083537, 2021). "On the other hand, the role of STAT1 as a tumor suppressor has been demonstrated in human breast cancer." (PMID 32754201, 2020). "The inducible overexpression of PTPN2 not only repressed IFNγ‐induced p‐STAT‐1 and Cxcl9/10 expression, but most importantly also the recruitment of PTPN2‐deficient CAR T cells to HER‐2‐E0771 mammary tumours in vivo." (PMID 31803974, 2020). "Co-expression analysis of PLSCR1 with other genes in a gene expression dataset (E-TABM-157) that contains 51 breast cancer cell lines showed that PLSCR1 expression positively correlated with STAT1 expression." (PMID 32292520, 2020). "We previously reported that IFN-β stimulates cytotoxicity through the JAK/STAT1 pathway in MCF-7 human breast cancer cells." (PMID 32210710, 2020). "Chronic stimulation of CD95 on breast cancer cells can increase their cancer initiating capacity through activation of a type I interferon (IFN-I)/STAT1 pathway when caspases are inhibited." (PMID 31992798, 2020).
breast cancer (continued). "Two downstream markers of STING activation, namely activating phosphorylations of STAT1 (pTyr701-STAT1) and of NF-κB (pSer536-p65) were induced in breast cancer cell lines treated with the antimitotic agent paclitaxel in vitro." (PMID 31937780, 2020). "It has been reported that STAT1 promotes breast cancer progression by increasing cancer stemness 11 and contributes to radioresistance in breast cancer-initiating cells." (PMID 32292520, 2020). "BHLHE40 promotes PI3K/Akt/mTOR activation in breast cancer, activating tumor progression, but suppresses STAT1 expression in clear cell carcinoma, triggering tumor suppression." (PMID 32577154, 2020). "In breast cancer, the source of IL-30 was stromal leukocytes, and IL-30 stimulated the proliferation of breast cancer cells in a gp130/IL-6R- and STAT1/STAT3-mediated mechanism." (PMID 32023849, 2020). "Crucial signaling behind stromal communication with breast cancer cells is represented by the transcription factor STAT1, which is able to enlarge tumorigenicity and chemoresistance." (PMID 30871158, 2019). "Increased STAT1/Notch signaling predicted clinical resistance to chemotherapy and radiotherapy in breast cancer." (PMID 31101063, 2019). "Specific genes that have been identified as drivers of stemness of breast cancer stem cells, such as interferon‐related developmental regulator 1 (Ifrd1) and Stat1, were among the upregulated genes." (PMID 31069797, 2019). "STAT1 is overexpressed in many types of cancers, including leukemia, breast cancer, squamous cell carcinoma of the head and neck (SCCHN), glioma, renal cell carcinoma, prostate cancer and soft tissue sarcoma." (PMID 30709063, 2019). "We have previously reported in patients that a pretreatment STAT1 signature was associated with better prognosis in TNBC and HER2+ breast cancers and with better response to neoadjuvant chemotherapy." (PMID 30546090, 2019). "Subsequent activation of STAT1 facilitated Notch signaling in breast cancer cells inducing a radiotherapy resistant stemcell-like phenotype." (PMID 31101063, 2019). "CAF are able to secret exosomes through the receptor RIG-1 and activate STAT1 in breast cancer cells; in turn, STAT1 activation further activates NOTCH3, leading to increased drug resistance in CSCs." (PMID 31505803, 2019). "In summary, breast cancer stroma-related genes, including JUN, FOS, ATF3, STAT1, COL1A1 and FN1, were all associated with tumor invasion and metastasis." (PMID 30237810, 2018). "This is firstly reported that miR-29c inhibited the proliferation, migration, invasion colony, and 3D growth of breast cancer cells by targeting TIMP3/STAT1/FOXO1 pathway." (PMID 29796115, 2018). "All together, these results suggest that miR-29c inhibits breast cancer by targeting the DNMT3B/TIMP3/STAT1/FOXO1 pathway." (PMID 29796115, 2018). "Another study showed that the growth of therapy resistant cancer stem cells was promoted due to STAT1 dependent antiviral signaling activated by exosomal transfer of RNA between stromal and basal breast cancer cells, which also correlated with IRDS expression." (PMID 30186768, 2018). "The present study offers a possible mechanism by which the JAK‐STAT pathway component STAT1 is involved in regulating oestrogen signalling activity and modulating tamoxifen sensitivity in breast cancer cells." (PMID 30334368, 2018). "STAT1 is necessary to maintain ERα signalling in breast cancer cells, probably by regulating ERα gene expression." (PMID 30334368, 2018). "As STAT1 is involved in breast cancer pathways, the increase in breast cancer is likely due to STAT1’s role in tumorigenesis instead of immune surveillance." (PMID 29881389, 2018). "Previous study reported that increased STAT1 expression and high STAT1 activation (p-STAT1 protein levels) were related to a favorable prognosis in breast cancer." (PMID 29326301, 2018). "In order to assess the effect of STAT1 on breast cancer cell proliferation, STAT1 was depleted in MCF‐7 and LCC2 cells." (PMID 30334368, 2018).